CCL2 (C-C motif chemokine ligand 2)
Diseases named in the same sentence as CCL2 in open-access papers (continued):
Sharing a sentence is not in itself a finding about the gene and the disease.
infection (continued). "In both infection models, the increase in CCL2 expression led to an increase in the proportion of Ly6Chi monocytes in the liver, but with different localization in the affected tissue." (PMID 36010615, 2022). "CCL2 is a chemokine capable of recruiting monocytes, memory T cells, and dendritic cells to sites of tissue injury and infection, suggesting maintenance of granuloma integrity in asymptomatic patients." (PMID 36142557, 2022). "The chemokine receptors CCR2 (CCL2/MCP-1 receptor) and CCR5 (CCL3/MIP-1A receptor) in deficient mice exhibit defects in directing inflammatory cells to airways after infection." (PMID 36119044, 2022). "Infection also led to upregulation of the CCL2 chemokine and the IL-18 pro-inflammatory interleukin." (PMID 33921891, 2021). "It was found that Rufomycin 4–7 treatment significantly decreased the Mabs-R-induced gene expression of various proinflammatory cytokines and chemokines (Tnfa, Il1b, Il6, Cxcl5, Ccl2, and Ccl4) in BMDMs at 6 h post-infection (hpi)." (PMID 34447358, 2021). "Consistently, the paired production of the IFNγ cytokine and the CCL2 chemokine in response to infection remained unchanged, when compared to mice receiving WT bradyzoite-loaded cysts." (PMID 33557824, 2021). "To determine the role of TNC in the development of systemic inflammation, we measured the plasma levels of TNF-α, IL-6, and CCL2 as markers of systemic inflammation 24 and 42 h after the beginning of infection." (PMID 33776992, 2021). "Of these ligands, we found that CCL2 is mainly produced by activated monocytes, which are positioned at infection foci and thereby contribute to reinforcement of the cDC network next to the antigen source." (PMID 34739343, 2021). "The exosomes secreted by microglia during TMEV infection also induced the expression of pro-inflammatory cytokines, IL-6, IL-12, and TNFα, and chemokines, CCL2, in bystander uninfected microglia." (PMID 34485270, 2021). "The pro-inflammatory molecules that increased in the CNS during the infection are most commonly IL-6 and CCL2." (PMID 33917837, 2021). "In contrast, mice treated with D. pigrum 040417 had significantly reduced levels of BAL TNF-α and CCL2 compared with controls after 32 hours post-infection." (PMID 34207076, 2021). "Lower magnitudes of gene regulation was noted in this study after infection compared to ferrets infected with the H1N1 virus A/California/07/2009 although immune response genes such as CCL2, CCL8, CXCL9, and CXCR1 increased over the time course." (PMID 34267262, 2021). "One study reported that CCL2 expression increases rapidly in the early acute phase of infection and then progressively decreases as the disease advances." (PMID 34205807, 2021). "The immune response against the HSV-1 in the murine ENS appears highly coordinated and characterized by the activation of the innate immune system at the early time of infection when macrophages are recruited in the ENS by the CCL2/CCR2 pathway." (PMID 34094993, 2021). "In fact, our findings demonstrated an increase in heart CCL2 expression and the number of inflammatory cells in the heart and adipose tissues following infection in all dietary groups." (PMID 34113663, 2021). "Infected mice receiving all diets presented comparable levels of recruited inflammatory cells at 30 days post-infection but, at this time, we observed lard diet inducing an overproduction of CCL2 in the cardiac tissue and its inhibition in the adipose tissue." (PMID 34113663, 2021). "Newly-generated cDCs expressing CCR2 are retained at foci of infection by CCL2 until they contact virus or virus-infected cells, which act as a source of antigen and activation signals." (PMID 34739343, 2021). "In both TLR4WT and TLR4mut mice, there was still a significant induction of BBB permeability, ICAM-1, MMP-2 and CCL-2 in the brains during VEEV TC-83 infection." (PMID 33487119, 2021).
infection (continued). "In the bulk RNA-seq of BALF, the expression of several proinflammatory mediators with known hDRG receptors seem upregulated after severe infection, including CCL2/3/4/7/8 and CXCL1/2/6." (PMID 33458558, 2021). "The levels of cytokines (IL-6, TNF-α, IL-1β) and chemokine (CCL2) were upregulated in response to the B.1.1.7 and B.1.351 infection in the lungs." (PMID 35062231, 2021). "CCL2 belongs to the CC chemokine family and is a chemoattractant for recruiting monocytes, memory T cells, and dendritic cells to infection sites." (PMID 34452435, 2021). "Although the lard diet increases the heart CCL2 production after infection compared with infected normolipidic group, the number of inflammatory cells in the tissue is similar among the infected groups independent of the dietary type." (PMID 34113663, 2021). "RIPK3-deficiency interfered with the secretion of certain cytokines upon MVA-infection as well as with constitutive CCL2-secretion." (PMID 34711816, 2021). "Our previous studies have indicated that primary cultures of alveolar epithelial cells type II from naïve mice had increased expression of epithelial cell-derived cytokines IL-33, TSLP and CCL2 after in vitro infection with RSV." (PMID 33923693, 2021). "Nevertheless, MIG/CXCL9, IP-10/CXCL10, I-TAC/CXCL11, BLC/CXCL13 and JE/MCP-5/CCL2 detected in kidney of C3H-HeJ mice at 24h post infection was also detected in serum/blood cells in our study." (PMID 34249775, 2021). "The CCL2 level moderately increased at 8 h, reached a peak at 16 h and was persistent throughout 48 h post-infection." (PMID 34368012, 2021). "Mice fed with the normolipidic diet presented with an increased production of CCL2 in adipose tissue after infection compared to all other dietary group despite this, the tissue inflammation increased similarly for all groups." (PMID 34113663, 2021). "Those that were significantly higher in the vehicle mice at the late stage of infection included the monocyte and neutrophil chemoattractants CCL2, CCL4, and MIP-2a." (PMID 34835277, 2021). "Mincle-/- MΦ infected with live bacteria produced significantly less Cxcl1 and Ccl2 early in infection than WT cells, indicating this receptor plays a role in propagating inflammation." (PMID 34320039, 2021). "Similar to our findings from the lethal infection model, treatment with L. plantarum resulted in significant reductions in the levels of immunoreactive IL-6, CCL2, and CXCL10 detected in the BAL fluid of mice inoculated with a sublethal dose of PVM." (PMID 34959580, 2021). "Several chemokines were induced quickly in the early phase (day 2 p.i.)and maintained at a rather high level through the first week of infection, including CCL2, CCL3, CCL4, CCL7, CXCL10, IL-6, IFN-γ, CCL11, CCL5, TNF-α, CXCL1, IL-4, IL-12p70." (PMID 34379705, 2021). "The failure of CCL2-Y92A to protect plants from infection indicates that the carbohydrate-binding activity of CCL2 is essential for the observed protection." (PMID 33897746, 2021). "Analysis of proinflammatory cytokine/chemokine profiles during the acute phase of infection between days 14 and 16 post challenge showed marked increases of G-CSF, GM-CSF, IL-1β, IL-4, IL-8, IL-12/23 (p40), IL-18, MCP-1/CCL2, SCD40L, TGF-α, and VEGF." (PMID 34451491, 2021). "This indirect pathway of neutralising bacteria by platelets, additionally includes the migration process of PMN and MN cells, activated by IL-8 (CXCL-8) and MCP-1 (CCL-2) secreted by activated platelets during infection with α-toxin from Staph. aureus." (PMID 34970260, 2021). "The infection increased the CCL2 production in the heart tissue and the number of inflammatory cells infiltrating the tissue independently of the diet administered." (PMID 34113663, 2021). "The murine infection model for the disease is characterized by CCL2/CCR2-dependent recruitment of Ly6Chi monocytes to the liver, and an increase in granuloma-associated resident CX3CR1+ macrophages." (PMID 33829283, 2021).
infection (continued). "What’s more, either SARS-CoV-2 or it’s variants infection, Meplazumab treatment had a favorable therapeutic effect on the downregulation of cytokines and chemokines at 6 d.p.i., such as IL-6, IL10, IL1b, CCL2, CXCL1, CXCL2, IFN-γ, IL-17, and CyPA." (PMID 34564690, 2021). "More importantly, we found that such TNFα-mediated enhancement during infection was 2- to 3-folds reduced in Mincle-/- MΦs (Il27, Cxcl10, Ccl2), implying the mitigation of proinflammatory responses." (PMID 34320039, 2021). "CCL2 expression and monocyte recruitment in this infection model is dependent on initiation of the IL-23/IL-17 axis." (PMID 33829283, 2021). "For example, CCL2-mediated chemotaxis is critical for tissue recruitment of monocytes/ macrophages upon inflammation and infection." (PMID 33138863, 2020). "Chemokines produced during the course of RSV infection have been linked to disease severity, including CXCL1, CCL2 and CCL5, either in murine models of infection or in patients." (PMID 32107411, 2020). "Previous in vivo studies following experimental infection with Ab4-wt (neuropathogenic) strain showed release of fewer cytokines/chemokines at low concentration (IL-10, CCL2, CCL3) in comparison to RacL11 and NY03 strains (abortigenic strains)." (PMID 32911663, 2020). "The anti-inflammatory cytokines (interleukin-4 [IL-4], IL-6, and IL-10) and MCP-1/CCL2 were detected early after P. yoeliiyoelii 17XNL infection." (PMID 32958528, 2020). "Presently, the induction level of IL-1β, CXCL1 (KC), CXCL2 (MIP-2), and CCL2 (MCP-1) mRNA in the lungs after infection was significantly higher in klotho KO mice than in klotho WT mice." (PMID 33329595, 2020). "An interesting finding was that some mediators were more affected by TLR2 loss in the brain compared to the galea, including IL-1β, CCL2, TNF-α, IL-6, and CXCL2, which was particularly evident at day 14 post-infection." (PMID 32290861, 2020). "In the spinal cord, WT-infected mice had higher levels of Il6, Tnf, Ccl2, and Ccl5 mRNAs at 2 or 4 days after infection, while Il1β was highest in Y114A at 2 and 6 days (P < 0.01 versus G32S, P < 0.0001 versus Y114A)." (PMID 32047134, 2020). "On the other hand, CCL2−/− mice have impairments in recruiting monocytes to sites of infection, though the number of circulating leukocytes is similar to WT mice." (PMID 32546752, 2020). "In a murine model of caecal ligature and puncture-induced infection, higher levels of CCL2 modulates peritoneal bacterial clearance, suggesting CCL2 is important in antimicrobial defence." (PMID 32407417, 2020). "The MCP-1 (CCL2) release was also stimulated after infection in both mouse strain, in a similar fashion." (PMID 33255176, 2020). "The levels of mRNAs for chemokines Ccl2, Ccl5, and Cxcl10 remained higher at 6 days after infection in spinal cords of Y114A-infected than WT-infected mice (P < 0.0001)." (PMID 32047134, 2020). "On the other hand, PTB cases with the CCL2-2518 GG genotype were having lower concentration of CCL2 thus lowering the production of IFN-γ and becoming susceptible to infection due to poor Th1 response." (PMID 33381602, 2020). "Brain CCL2 levels were increased in both sexes 24 h after infection, but increased only in males at 5 d post infection." (PMID 32373108, 2020). "Reported associations of CCL2, CXCL9 and CXCL10 polymorphisms with the incidence of infection and severity of SARS have been inconsistent." (PMID 33613280, 2020). "CCL2 was first identified as a monocyte-specific chemoattractant to sites of injury and infection, although its activity appears to be far more pleiotropic." (PMID 32849592, 2020). "In humans, PON-1 activity and CCL-2 concentration have an inverse correlation during natural infection and CCL-2 decreases together with the increase of PON-1 and the resolution of naturally occurring septic processes after several days of hospitalisation." (PMID 33148245, 2020).
infection (continued). "K18-hACE2 SARS-CoV-2 infected mice showed elevated levels of Il6, Ccl2, and Cxcl10 at day 2 post-infection, which returned to baseline by day 5 post-infection." (PMID 33073694, 2020). "At 5 days post infection, there was still an increase in CCL2 in infected males (2.1-fold, p = 0.006), although less augmented than at 24 h." (PMID 32373108, 2020). "Pulmonary concentrations of pro-inflammatory cytokines and chemokines (e.g. IL-6, IFNγ, and CCL2) broadly increased in response to infection at 3 and 9 dpi, and then declined following control of viral replication at 14 dpi." (PMID 32645119, 2020). "Functional cytokine assays on sorted monocyte populations show that the infection-distinguishing monocytes secrete high levels of chemokines, such as CCL2 and CXCL5." (PMID 33273621, 2020). "Through signalling via CCR2 and CCR4 receptors, CCL2 mediates chemotaxis of monocytes and dendritic cells, as well as memory T cells to the sites of inflammation upon tissue injury or infection." (PMID 32295518, 2020). "CCL2 levels in the brain ranged from 6.2 to 255 μg/ml at 24 h, but from 1.5 to 17.1 μg/ml at 5 d after infection." (PMID 32373108, 2020). "IL-1β, CXCL1, CXCL2, and CCL2 expression was significantly higher in the lungs of klotho KO mice infected with A. baumannii than in those of klotho WT mice at 1 day post-infection." (PMID 33329595, 2020). "CCL2 is a chemokine which stimulates monocyte recruitment to the infection site by binding to the E-box present on the Ccl2 gene promoter region." (PMID 32012898, 2020). "Transcription analyses at 4 h post infection revealed an over 30- and 1,000-fold increment in the transcription of the chemokine genes Ccl2 and Cxcl2, respectively." (PMID 33117382, 2020). "CXCL2 (MIP‐2) and CXCL1 (KC), which are responsible for the infiltration of neutrophils and monocytes, were suppressed at the beginning of infection (6 h), whereas inhibition of CCL2 (MCP‐1), TNF‐α, IL‐6, IL‐1β and IL‐17A appeared after 24 h." (PMID 33014369, 2020). "The level of CCL2 mRNA in the lungs at 1 day post-infection was significantly higher in klotho KO mice than in klotho WT mice." (PMID 33329595, 2020). "CCL2 is one of the main chemokines involved in inflammation-dependent recruitment of monocytes to sites of infection." (PMID 32038652, 2019). "As shown, both TNFAIP3-KO cell clones (KO#20 and KO#03) showed significant higher levels of proinflammatory factors like TNF-α, IL-6, IL-1β, and CCL2 in response to the infection, as compared to that of the wild-type cells." (PMID 31783671, 2019). "For example, chemokine genes, such as Ccl2, 5, 7, and 12, were induced following infection with VACV-WR, yet to a lesser extent than following VACV-Wyeth infection." (PMID 30759813, 2019). "Because monocyte recruitment is due to CCL2 production, we examined its expression in the CNS during the chronic phase of infection." (PMID 31555297, 2019). "Using this in vitro cell system, two genes were identified that were more strongly induced during infection with a virulent strain (IL-8 and CCL2), and these are strong candidates for further in vivo studies." (PMID 31664929, 2019). "The chemokine CCL2 is best known to regulate macrophage recruitment during wound healing, infection and inflammatory diseases." (PMID 31208996, 2019). "Various chemokine genes, responsible for the control and recruitment of immune cells to the site of infection (i.e., Ccl2, Ccl4, Ccl5, Ccl7, Ccl8, Ccl12, and Ccl19), were also significantly upregulated in the VACV-Wyeth infected brains on 4 d.p.i." (PMID 30759813, 2019). "The infection of human macrophages induced the expression of pro-inflammatory cytokines/chemokines such as MCP-1/CCL-2, IFN-α2, IFN-γ, MIP-1α/CCL-3, IP-10/CXCL-10, RANTES/CCL-5, IL-8, TNF-α, IL-12p40, and IL-6." (PMID 30984127, 2019). "Transcripts encoding the chemokines CCL2, CCL3 (MIP-1α), IL8, and CXCL13 showed the greatest abundance 24 h after infection with either Makona or RESTV." (PMID 31689981, 2019).
infection (continued). "We found that CCL2 induced by HIV-1 clade B (HIV-1B) infection of macrophages enhanced virus production, while CCL2 immuno-depletion reversed this effect." (PMID 31172941, 2019). "The chemokines CCL5, CCL9, CXCL10, and CCL2 attract immunity cells at the site of infection and their production is stimulated by TNF-α and boosts the production of NO by MΦ." (PMID 31508399, 2019). "The expression of genes encoding major inflammatory determinants tested including cytokine interleukin-6, complement component C3, and chemokine CCL2 declined from the high levels 15 days after infection to control values 60 days after infection." (PMID 31266862, 2019). "CCL2/MCP1 promotes effector responses by recruiting monocytes, memory T cells, and DC to sites of inflammation produced by tissue injury and infection." (PMID 31741710, 2019). "We infected these cells with wild type HIV-1BADA virus, in the presence of CCL2, α-CCL2 or an isotype antibody and measured virus production at day 15 post-infection." (PMID 31172941, 2019). "(E) CEM-CCR5 cells with ALIX knocked-down were infected with HIV-1BADA, either in the presence of CCL2, α-CCL2 or Isotype antibody followed by measurement of virus replication at 12 days post-infection." (PMID 31172941, 2019). "Expression of Ccl2 was induced on day 5 after NMII infection and showed a clear dependence on MyD88." (PMID 30800124, 2019). "During physiological host defense, for example upon tissue injury or infection, CCL2 expression is induced by inflammatory stimuli and promotes extravasation of effector cells from the blood stream across the endothelium." (PMID 31921102, 2019). "Furthermore, in an intraperitoneal infection model, Dectin-1 knockout mice were less able to recruit neutrophils, monocytes, and eosinophils to the site of infection than wild-type mice and this was associated with a decrease in IL-6, CCL2, CCL3, G-CSF, and GM-CSF production." (PMID 32047726, 2019). "In contrast, MCP-1/CCL2 (2-fold) showed increased levels in infected macrophages (24 h of infection) compared to uninfected macrophages." (PMID 30949455, 2019). "In sera, only the peak concentrations of Cxcl1 (8 h), Ccl2 (8 h), Ccl3 (8 h), IL-1β (4 h), and IL-6 (4–8 h after infection) were significantly elevated in ExoY-infected mice as compared to ExoYK81M-infected mice." (PMID 29734720, 2018). "Plasma levels of TNF-α, IFN-γ, IL-6, IL-10, CXCL10, CCL2 and IL-4 were all increased upon infection." (PMID 30375380, 2018). "Increased levels of D-dimer, IL-6, sCD14, CXCL10, TNF-α, IL-18, and CCL2 among others have been shown to be increased during acute infection or chronically increased throughout infection." (PMID 29391069, 2018). "While TNF-α and IL-6 production increased in sole microglia post-infection, CCL2 and IL-1b were upregulated only in μBS." (PMID 30619100, 2018). "This unique chemokine profile targets different populations of immune cells like dendritic cells, T cells, and B cells by CCL20, neutrophils by CXCL1 to CXCL3, and macrophages and T-cells by CCL2 to the site of infection." (PMID 29726306, 2018). "The portal region was particularly impacted during infection characterized by massive infiltration of immune cells, production of CCL2, and high levels of SIV-RNA positive cells." (PMID 29466439, 2018). "GM-CSF promotes myeloid differentiation toward inflammatory, M1-like macrophages, and CCL2 promotes monocyte/macrophage recruitment to sites of tissue injury or infection." (PMID 29649002, 2018). "Transcription of inflammatory cytokines (e.g., cxcl, ccl2, 1l1a, and il1b) peaked at 1.5 and 3 h of infection." (PMID 30062089, 2018). "Infection studies that used CCL2−/− and CCR2−/− C57BL/6 mice suggested that CCL2 is dispensable for protection against L. major, but that another CCR2 ligand is required." (PMID 29097502, 2018). "Oral epithelial cells were shown to express various cytokines and chemokines such as TNF-α, IL-1β, and CCL2 that were upregulated upon infection in our study." (PMID 29967614, 2018).